VEGFC (vascular endothelial growth factor C)
Diseases named in the same sentence as VEGFC in open-access papers (continued):
Sharing a sentence is not in itself a finding about the gene and the disease.
depression (4 papers, 2018 to 2025). "In the context of subchronic variable stress, intracisternal delivery of adeno-associated virus serotype 1 vector encoding vascular endothelial growth factor C, which enhances meningeal lymphatics, was shown to alleviate stress-induced depression-like behaviors in female mice." (PMID 40809378, 2025). "Taken together, these results suggest that improvement of meningeal lymphatics by intracisternal injection of AAV overexpressing VEGFC in the dura mater prevented stress-induced depression- and anxiety-like behaviors in female mice." (PMID 35974004, 2022). "Upregulation of ACSL3 via adenovirus in aged 3xTg-AD mice led to increased protein levels of brain-derived neurotrophic factor (BDNF) and vascular endothelial growth factor C (VEGF-C) (via brain histology, capillary-based immunoassay), resulting in alleviation of depression and anxiety symptoms." (PMID 39532829, 2024). "VEGFC has not yet, to our knowledge, been investigated in depression, however it belongs to the same protein family of VEGF, and the two were highly correlated (p < 0.001)." (PMID 30190686, 2018).
diabetic retinopathy (4 papers, 2012 to 2022). "A study of 1 919 diabetic patients with gene polymorphisms found that three SNPs (rs17697419, rs17697515, and rs2333526) of VEGFC are associated with diabetic retinopathy." (PMID 35865663, 2022).
fibrosarcoma (4 papers, 2010 to 2024). A malignant mesenchymal fibroblastic neoplasm affecting the soft tissue and bone. "Others have shown that tumor cells influence lymphatics by secreting vascular endothelial growth factor C (VEGF C), and increases in the diameter of adjacent lymphatics have been observed after implantation of VEGF-C overexpressing fibrosarcoma xenografts in the tip of the mouse ear." (PMID 33606081, 2021).
Hyperglycemia (4 papers, 2012 to 2024). An increased concentration of glucose in the blood. "In prostate PC-3 cancer cells, hyperglycemia triggers enhanced vascular endothelial growth factor-C (VEGF-C) expression via the LPAR1/3-Akt-ROS-LEDGF signaling." (PMID 34209775, 2021).
leukemia (4 papers, 2007 to 2025). A malignant (clonal) hematologic disorder, involving hematopoietic stem cells and characterized by the presence of primitive or atypical myeloid or lymphoid cells in the bone marrow and the blood. "MSC also secrete a number of cytokines, chemokines, and growth factors (e.g., VEGFC, TGF‐β1, TGF‐ β2, GDF6, SDF1, and IL‐6) that can further modulate the interaction between leukemia cells and MSC." (PMID 40682336, 2025).
liver cancer (4 papers, 2014 to 2024). An epithelial or non-epithelial malignant neoplasm that arises from the liver. "The expression changes of VEGFC/D-VEGFR3/NRP2 and SDF1/CXCR4 are almost completely identical between tumor cells and normal cells, between high and low lymph node metastatic potential of liver cancer cells as well as between downregulation and upregulation of AnnexinA7 (unpublished data)." (PMID 29783989, 2018).
Milroy disease (4 papers, 2018 to 2023). Milroy disease is a frequent form of primary lymphedema (see this term) characterized generally by painless, chronic lower-limb lymphedema found at birth or developing in the early neonatal period. "In summary, most patients with Milroy disease have pathogenic variants in the VEGFR3 gene, but mutations in the ligand known as VEGFC can also give rise to a very similar disorder." (PMID 30071673, 2018).
Myocardial fibrosis (4 papers, 2022 to 2026). "Two weeks later, echocardiography and lymphatic counts were performed, and the extent of myocardial fibrosis and the expression of vascular endothelial growth factor C (VEGFC) and VEGF receptor 3 (VEGFR3) were determined." (PMID 35188856, 2022).
myocardial ischemia (4 papers, 2022 to 2025). A disorder of cardiac function caused by insufficient blood flow to the muscle tissue of the heart. "Of relevance to cardiac ischemia, hypoxia-inducible transcription factors have been reported to coordinate lymphangiogenesis and VEGFC induction during wound healing." (PMID 35271504, 2022). "Additionally, the local delivery of VEGFC using a hydrogel was found to improve lymphatic function and decrease infarct scar size in mice subjected to myocardial ischemia." (PMID 41221452, 2025).
acute myeloid leukemia (3 papers, 2012 to 2020). Acute myeloid leukemia (AML) is a group of neoplasms arising from precursor cells committed to the myeloid cell-line differentiation. "mRNA expression levels of VEGFC (contrary to other VEGFs isoform), PI3K, AKT, mTOR, MEK1, PTEN,IL6, LC3 and P62 genes were upregulated in acute myeloid leukemia (AML) cells following treatment with ATO/THAL." (PMID 31721534, 2020).
amyloid (3 papers, 2023 to 2025). "Enhancement of meningeal lymphatic drainage by vascular endothelial growth factor C (VEGFC), DSCR1, immunotherapy, and physical stimulation treatment to accelerate Aβ clearance in the brain could ameliorate cognitive dysfunction in an aging mouse model of amyloid pathology (5XFAD) 16,18-20." (PMID 36593948, 2023).
asthma (3 papers, 2022 to 2023). "Remodeling of airway lymphatic vessels is seen in asthma and in animal models has been shown to be mediated by VEGFC, VEGFD and TNF-alpha." (PMID 36999077, 2023). "Interestingly, despite elevated levels of VEGFC and VEGFD, decreased lymphatic vessel density is associated with airway edema and fibrotic changes, and has been reported in fatal asthma cases, suggesting that anti-lymphangiogenic factors may be more prominent in severe disease." (PMID 36999077, 2023).
colorectal tumor (3 papers, 2010 to 2013). "Recently, hsa-miR-27b was found to inhibit colorectal tumor progression and angiogenesis, through targeting VEGFC." (PMID 24312312, 2013).
COVID-19 (3 papers, 2022 to 2024). A disease caused by infection with severe acute respiratory syndrome coronavirus 2. "Compared with the control data, LAMA4 and VEGFC were highly expressed in children with myocarditis and COVID-19, whereas APOE and TNFRSF9 were expressed at low levels." (PMID 39026189, 2024).
skin inflammation (3 papers, 2021 to 2025). "Vascular endothelial growth factor-C contributes to the development of skin inflammation in obese individuals, and intradermal injection of recombinant vascular endothelial growth factor-C enhances lymphangiogenesis and lymphatic function, leading to the suppression of cutaneous inflammation." (PMID 34069063, 2021).
thyroid (3 papers, 2012 to 2016). "Regarding the selected genes in other CNA/UPD areas, the AKT3/PIK3CA pathway, the KRAS/RAP1B/RAP1GAP/BRAF pathway, and the VEGFC pathway have been known to participate in thyroid carcinogenesis/cancer progression." (PMID 22558328, 2012).
triple-negative breast carcinoma (3 papers, 2014 to 2024). An invasive breast carcinoma which is negative for expression of estrogen receptor (ER), progesterone receptor (PR), and human epidermal growth factor receptor 2 (HER2). "Hence, combining anti-VEGF and anti-VEGFC appears to be relevant for the treatment of triple negative breast cancers for which VEGFC/VEGFR3/NRP1 signaling is detrimental." (PMID 34067671, 2021). "We observed that several cell lines representative of triple negative breast cancers, including MDA-MB231 cells, over-express VEGF and VEGFC." (PMID 34067671, 2021).
astrocytoma (2 papers, 2018 to 2020). "Interestingly, VEGFC and THSD4 were expressed significantly less in GBMs than in astrocytoma II samples." (PMID 32346064, 2020).
autoimmune disease (2 papers, 2022 to 2025). A disorder resulting from loss of function or tissue destruction of an organ or multiple organs, arising from humoral or cellular immune responses of the individual to their own tissue constituents. "In autoimmune diseases, VEGFC has shown a positive correlation with inflammatory cytokines, indicating a potential role in promoting inflammatory activation in autoimmune or autoinflammatory diseases." (PMID 38980684, 2025).
cervical intraepithelial neoplasia (2 papers, 2008 to 2019). "In the context of high-risk HPV infection, VEGFC expression was stimulated by cigarette smoke and associated with the grade of cervical intraepithelial neoplasia." (PMID 31766385, 2019).
chronic heart failure (2 papers, 2020 to 2023). "In addition, human heart samples were obtained from healthy donors or patients with chronic heart failure, and the gene expression of lymphatic endothelial markers VEGFC, LYVE1, PDPN, and FLT4 was assessed." (PMID 33200983, 2020).
dementia (2 papers, 2023 to 2024). Loss of intellectual abilities interfering with an individual's social and occupational functions. "In a comparative analysis of gene expression in MRI type 2, we found a decrease in the expression of ACOX1, BIN1, CD2AP, CD33, TNFR1, VEGFA, and VEGFC genes in clinically significant CI (MCI and dementia) compared to the control group." (PMID 39125683, 2024).
endometrial cancer (2 papers, 2003 to 2013). Primary or metastatic malignant neoplasm involving the endometrium (mucous membrane that lines the endometrial cavity). "Vascular endothelial growth factor-C and VEGF-D have both been correlated with a poor prognosis in endometrial cancer, but the expression of VEGF-B has not been described." (PMID 12942123, 2003).
experimental autoimmune encephalomyelitis (2 papers, 2019). An autoimmune demyelinating disease of the central nervous system that is produced experimentally in animals by the injection of homogenized brain or spinal cord in Freund's adjuvant. "We report that lymphatic vessels near the cribriform plate undergo lymphangiogenesis in a VEGFC – VEGFR3 dependent manner during experimental autoimmune encephalomyelitis (EAE) and drain both CSF and cells that were once in the CNS parenchyma." (PMID 30651548, 2019).
infarct (2 papers, 2011 to 2012). "Except for VEGFC at 24 h after cerebral infarct, which was lower, the other VEGF genes (A and B) were not significantly altered at either time-point." (PMID 23284893, 2012).
medulloblastoma (2 papers, 2020). A malignant, invasive embryonal neoplasm arising from the cerebellum. "We provide evidence supporting that the VEGFC/VEGFC receptor axes and associated lymphangiogenesis exert a beneficial effect in pediatric medulloblastoma, unlike the admitted dogma." (PMID 33067561, 2020).
Merkel cell carcinoma (2 papers, 2022). "Reports about Merkel cell carcinoma, a highly malignant cutaneous neuroendocrine tumor, indicated that M2 expresses high levels of vascular endothelial growth factor-C (VEGF-C), which can promote lymphangiogenesis." (PMID 36741415, 2022).
myocarditis (2 papers, 2023 to 2024). Myocarditis is a condition that is characterized by inflammation of the heart muscle (myocardium). "Macrophage efferocytosis also promotes the resolution of myocarditis by inducing VEGFC production." (PMID 37047321, 2023).
neovascular glaucoma (2 papers, 2021 to 2024). "In this regard, our in silico analysis also identified VEGFC, which was found to be upregulated in the trabecular meshwork of patients with POAG and neovascular glaucoma." (PMID 39458974, 2024).
pancreatic adenocarcinoma (2 papers, 2016 to 2019). "In murine 4T1 and LLC cells (breast and lung tumor, respectively), as well as in human CAPAN-1 pancreatic adenocarcinoma, the VEGFA and VEGFC IRESs are activated after 24 hr of hypoxia whereas the EMCV IRES is not activated." (PMID 31815666, 2019).
periodontitis (2 papers, 2021). An acute or chronic inflammatory process that affects the tissues that surround and support the teeth. "Vascular endothelial growth factor C (VEGFC), the main growth factor of lymphatic vessels, was found to be upregulated in tissues affected by periodontitis." (PMID 34445604, 2021).
preeclampsia (2 papers, 2021 to 2023). Preeclampsia is a hypertensive disorder of pregnancy that is characterized by new-onset hypertension with proteinuria presenting after 20 weeks of gestation, and depending on mild or severe forms may initially present with severe headache, visual disturbances, and hyperreflexia. "In white women, FLT1 rs722503, FLT4 rs307826, and VEGFC rs7664413 were significantly associated with preeclampsia." (PMID 36901702, 2023).
pulmonary arterial hypertension (2 papers, 2021 to 2022). Pulmonary arterial hypertension (PAH) is a group of diseases characterized by mean pulmonary artery pressure >20 mmHg and elevated pulmonary arterial resistance leading to right heart failure. "On the other hand, VEGFC levels are low in patients with systemic sclerosis, and VEGFC may be a useful indicator for early prediction of pulmonary arterial hypertension in those patients." (PMID 35865663, 2022).
renal carcinoma (2 papers, 2020 to 2021). A carcinoma arising from the epithelium of the renal parenchyma or the renal pelvis. "As a tumor suppressor in bladder and renal cancers, VEGFC, CTNNB1, and MAP2K1 were three targets of miR-1826 to mediate its inhibiting effect on tumorigenesis." (PMID 32104674, 2020). "Moreover, they inhibited the proliferation of VEGFC-expressing renal cancer cells through NRP2 signaling." (PMID 34067671, 2021).
type 1 diabetes (2 papers, 2017 to 2025). "In type 1 diabetic mice (induced by streptozotocin), systemic administration of AAV2/9 increased glomerular human VEGFC expression, ameliorating both albuminuria and increased glomerular permeability." (PMID 41058176, 2025).
uveal melanoma (2 papers, 2024 to 2026). A melanoma derived from melanocytes of the uveal tract. "In addition, targeting MLN4924 in uveal melanoma cells (UMs) can reduce the paracrine secretion of vascular endothelial growth factor-C (VEGF-C) in an NF-κB-dependent manner." (PMID 39062453, 2024). "Moreover, NAE1-mediated neddylation of CUL1 upregulates vascular endothelial growth factor C (VEGF-C) by augmenting NF-κB transcriptional activity, thereby facilitating tumor angiogenesis and uveal melanoma hepatic metastasis." (PMID 41540013, 2026).
acinar adenocarcinoma (1 paper, 2020). "Finally, high VEGFC expression was significantly correlated with an adverse OS (P = 0.003) and PFS (P = 0.01) in acinar adenocarcinoma, and a poor PFS (P = 0.01) in nonacinar adenocarcinoma." (PMID 32154654, 2020).
acute lymphoid leukemia (1 paper, 2025). "An understudied phenomenon is the overexpression of the RTK FLT4 and its specific ligand VEGFC, as well as its association with treatment failure, in pediatric acute lymphoid leukemia." (PMID 40316529, 2025).
adult-onset Still disease (1 paper, 2022). A rare inflammatory multisystem disorder characterized clinically by fever of unknown origin, arthralgia or arthritis, hyperleucocytosis, and typical skin rash. "In addition, serum VEGFC values are higher in adult-onset Still's disease, which may be a marker of disease activity." (PMID 35865663, 2022).
alveolar rhabdomyosarcoma (1 paper, 2012). A rapidly growing malignant mesenchymal neoplasm. "Analysis of the Genesapiens database of human transcriptomes demonstrated statistically significant up-regulation of VEGFC and EPHA2 in Ewing’s sarcoma, and ERBB3 in alveolar rhabdomyosarcomas." (PMID 23227212, 2012).
autoimmune thyroid disease (1 paper, 2022). Inflammatory disease of the thyroid gland due to autoimmune responses leading to lymphocytic infiltration of the gland. "We hypothesized that VEGFC gene is related to autoimmune thyroid diseases." (PMID 35865663, 2022).
cholesteatoma (1 paper, 2023). A pathologic process characterized by the proliferation of keratinizing squamous epithelium resulting in the accumulation of keratin and cells in the middle ear and/or mastoid. "In all analyzed samples, VEGFC and PDGFr, as well as pSTAT3, IL-1β, and TGF-β level expression, were basal in skin tissues with respect to cholesteatoma-related ones." (PMID 37623440, 2023).
Ewing sarcoma (1 paper, 2012). A small round cell tumor that lacks morphologic, immunohistochemical, and electron microscopic evidence of neuroectodermal differentiation. "Boxplot analyses providing comparisons within the different pediatric cancer samples indicated selective up-regulation of the mean expression of EPHA2 and VEGFC in Ewing’s sarcoma." (PMID 23227212, 2012). "EPHA2 (encoding EphA2, ephrin type A receptor 2), VEGFC (vascular endothelial growth factor-C), and FKBP1A (FK506 binding protein 1A) were overexpressed in Ewing’s sarcomas." (PMID 23227212, 2012). "In summary, we found that EPHA2 and VEGFC are highly expressed in pediatric Ewing’s sarcomas and ERBB3 in pediatric rhabdomyosarcomas." (PMID 23227212, 2012). "Fisher’s exact test demonstrated that the relative overexpression EPHA2 and VEGFC in Ewing’s sarcoma was 15- and 17-fold, respectively, when compared to all pediatric cancer and normal samples (P<0.001 for both comparisons)." (PMID 23227212, 2012). "In addition to EPHA2, we found that VEGFC expression was exceptionally high in pediatric Ewing’s sarcomas." (PMID 23227212, 2012).
glabellar hemangioma (1 paper, 2012). The most common variant of hemangioma which appears as a raised, red, lumpy area of flesh anywhere on the body, though 83% occur on the head or neck area. "Deletion of VEGFC may be associated with development of the glabellar hemangioma." (PMID 23320208, 2012).
herpesvirus infections (1 paper, 2022). "Both vascular endothelial growth factor-C (VEGF-C) and insulin-like growth factor binding protein-6 (IGFBP-6) have been shown to be upregulated during herpesvirus infections." (PMID 35911725, 2022).
inflammatory skin disease (1 paper, 2022). Inflammatory skin disorders covers a broad category that includes many conditions ranging in severity, from mild itching to grave medical health complications These disorders are common in people of all ages and races. "The relevance of ApoE, DKK1, IL12B, IL9, MANF, and VEGFC in specific inflammatory skin diseases was identified in several previous studies, as discussed further." (PMID 35393522, 2022).
macular edema (1 paper, 2025). "Additionally, we concentrated on several genes presumed to play a role in the pathophysiology of macular edema: VEGFA, VEGFC, EPO, NOS3 (eNOS), PLVAP, and APOE4." (PMID 40455044, 2025).
myxoid liposarcoma (1 paper, 2016). A liposarcoma characterized by the presence of round non-lipogenic primitive mesenchymal cells and small signet ring lipoblasts within a myxoid stoma with a branching vascular pattern. "As the expression of VEGFR3 was elevated in the myxoid liposarcoma cell lines, it is possible that targeting VEGFR3 and/or the ligands VEGFC or VEGFD would be beneficial." (PMID 27822137, 2016). "Our finding that a VEGFR3 ligand trap, which binds VEGFC and VEGFD, markedly inhibited the growth of myxoid liposarcoma cells confirms that soluble angiogenic factors at least partly drive the growth of these cells." (PMID 27822137, 2016).